USP18 (ubiquitin specific peptidase 18)
Diseases named in the same sentence as USP18 in open-access papers (continued):
Sharing a sentence is not in itself a finding about the gene and the disease.
tumor (continued). "USP18, an interferon stimulating response element, regulates IFN-α-mediated signaling in anti-viral immune response, but its role in IFN-γ-mediated tumorigenesis and anti-tumor immune response is unknown." (PMID 24884733, 2014). "Herein, we have demonstrated a gradient upregulation of USP18 in sorafenib-resistant HCC cells, xenografts, and tumor tissues obtained from patients who did not respond to sorafenib treatment." (PMID 40514377, 2025). "Mammary epithelial cells lacking USP18 induce the recruitment of Th1-subtype CD4 T cells by increasing IFN-γ-mediated Cxcl10 secretion, thus forming a tumor-suppressive microenvironment." (PMID 39334957, 2024). "Furthermore, analysis of The Cancer Genome Atlas (TCGA) revealed that in fifteen out of twenty-four tumor types, USP18 expression was markedly upregulated compared to the corresponding noncancerous tissues, which may also indicate higher IFN production in several types of tumor microenvironments." (PMID 36646704, 2023). "The mRNA levels of TGM2, USP18, DDX58, PARP9, STAT1 and STAT2 were not significantly different between ER--tumor tissues and their corresponding tumor-adjacent tissues." (PMID 29416786, 2018). "USP18 is a well-known negative feedback regulator of IFNAR signalling, but in non-induced, homeostatic conditions was reported to positively regulate cell cycle progression and even promote tumour growth and progression across different models." (PMID 38066598, 2023). "The upregulation of EFP, HERC5, UBA1 and USP18 in HCC tissues and the different patterns of correlation of the genes in HCC tumour and in adjacent non-tumour tissues suggest that these genes may play a role in the pathogenesis of HCC." (PMID 32132870, 2020).
cancer (47 papers, 2012 to 2026). A tumor composed of atypical neoplastic, often pleomorphic cells that invade other tissues. "Dysregulation of USP18 has been implicated in a spectrum of diseases, including autoimmune disorders, cancer, and neurological conditions." (PMID 41510264, 2025). "USP18 is a multifunctional protein and is implicated in a variety of pathological conditions including cancer." (PMID 38959043, 2024). "Enhanced levels of PLK2 correlated with high levels of caspase-3 and GSDME cleavage, a hallmark of pyroptosis, in IFN treated USP18-/- cancer cells." (PMID 38799433, 2024). "Prior research found that programmed loss of USP18 enhances ISGylation, whereas its augmentation reduces cancer growth by contributing to inflammation happen." (PMID 37658402, 2023). "Cancer-specific survival was longer in the low USP18 expression group than that in the high expression group, suggesting that upregulated USP18 is an important risk factor for cancer-specific death." (PMID 36771004, 2023). "Our study demonstrates that USP18 deficiency expands the landscape of ISGs, facilitating immunogenic, pyroptotic cancer cell death in vivo." (PMID 36646704, 2023). "USP18 is involved in pathogenic infections, inflammation, neurological disorders, and cancer by regulating IFN signaling and other substrates." (PMID 33919439, 2021). "A number of enzymes involved in the ISGylation process, namely E3 ligases (HERC5 and EFP/TRIM25) and USP18 have been shown to be associated with cancers via ISGylation-dependent and -independent mechanisms 15-18." (PMID 32132870, 2020). "We also highlight new insights into how USP18 is implicated not only in physiology but also in pathogenesis of various human diseases, involving infectious diseases, neurological disorders, and cancers." (PMID 32957626, 2020). "Increasing evidence has begun to demonstrate that USP18 is associated with the pathogenesis of cancer, even though the role of USP18 in tumorigenesis is still controversial." (PMID 32957626, 2020). "We also highlight new insights into how USP18 is implicated not only in physiology but also in pathophysiology of various human diseases involving infectious diseases, neurological disorders and cancers, suggesting the potential of therapeutic interventions for targeting USP18 for disease treatment." (PMID 32957626, 2020). "Similarly, depending on the substrate landscape, subcellular localization, cell type, and physiologic states, each cancer type may respond differently to USP18 loss or inhibition." (PMID 39843430, 2025). "In addition, Usp18 deficiency severely impairs cancer progression and improves survival." (PMID 39334957, 2024). "Thus, we hypothesised that loss of USP18 in cancer cell could also augment their sensitivity to ionising radiation." (PMID 33214684, 2021). "In this cancer, USP18 enhances the protein stability of zinc finger E-box-binding homeobox 1 (ZEB1) through the decreased ubiquitination of ZEB1, increasing the migration and invasion abilities of ESCC cells." (PMID 38675828, 2024). "Recently, studies have demonstrated the role of USP18 in the regulation of cancer proliferation, migration, and invasion." (PMID 38675828, 2024). "In colorectal cancer, USP18 enhances the proliferation of cancer cells by modulating the ubiquitination of the zinc finger protein SNAI1." (PMID 38675828, 2024). "Mechanistically, USP18 inhibits pyroptosis in cancer cells via enhancing ISGs, while USP48 promotes pyroptosis by stabilizing gasdermin E (GSDEM)." (PMID 39048965, 2024). "Among the atypical ISGs in IFN treated USP18 depleted cancer cells, we identified PLK2 as one mediator of the observed ICD." (PMID 38799433, 2024). "According to recent literature, several DUBs were reported to regulate pyroptosis in cancer, including USP18, USP24, and USP48." (PMID 39048965, 2024). "Different studies have demonstrated that USP18 is notably overexpressed in a variety of cancer types." (PMID 38455765, 2024).
cancer (continued). "Mechanistically, nuclear USP18 controls the enhancer landscape of cancer cells and diminishes STAT2-mediated transcription complex binding to IFN-responsive elements." (PMID 36646704, 2023). "Enhanced levels of PLK2 correlated with high levels of GSDME cleavage, a hallmark of pyroptosis, in IFN-treated USP18−/− THP-1 and MDA-MB-231 cancer cells." (PMID 36646704, 2023). "Again, Usp18 depletion had a significant survival benefit and fewer cancer (GFP+) cells were observed in the peripheral blood (PB) of Usp18+/Δ mice compared to their respective controls." (PMID 36646704, 2023). "Due to the USP18 deletion in cancer cells, chemotherapy, radiotherapy and IFN-α treatment induces more severe apoptosis and makes cancer cells more sensitive to those therapies." (PMID 37658402, 2023). "Lower USP18 expression correlates with better survival across human selected cancer types and delays cancer progression in mouse models." (PMID 36646704, 2023). "This study determined the mechanism by which targeting USP18 induces cancer pyroptosis through activating the production of a group of atypical IFN stimulated genes (ISGs) in addition to conventional ISGs." (PMID 37658402, 2023). "Again, Usp18 depletion had a significant survival benefit and fewer cancer (GFP+) cells were observed in the peripheral blood (PB) of SgCtrlUsp18+/Δ mice compared to SgCtrlUsp18+/f." (PMID 36646704, 2023). "To define the role of USP18 in cancer, we created a Usp18 conditional knockout mouse and find that Usp18 deletion severely impairs cancer progression and improves survival." (PMID 36646704, 2023). "Given these advantages, targeting USP18 in myeloid cells is potentially a promising therapeutic strategy across different types of cancers and warrants further investigation." (PMID 38100351, 2023). "In this study, we describe a role of nuclear USP18 in regulating cancer cell pyroptosis, a type of ICD." (PMID 36646704, 2023). "We only observed an enhanced IFN response in bone marrow cells of Usp18+/− mice relative to Usp18+/+ mice, supporting the feasibility of targeting Usp18 as a potential cancer therapy." (PMID 36646704, 2023). "In summary, we discovered that USP18 plays an essential role in regulating cancer immunogenic, pyroptotic cell death." (PMID 36646704, 2023). "Next, we noticed that three populations (Clusters 8, 9, 11) were significantly altered in transplanted cancer cells after Usp18 suppression." (PMID 36646704, 2023). "Among negative regulators of IFN signaling, we became interested in USP18 because low expression is correlated with better survival in several cancer types." (PMID 36646704, 2023). "By single-cell RNAseq analysis, we also uncover evidence that inhibition of USP18 specifically targets cancer stem cells, essential for relapse." (PMID 36646704, 2023). "Intracellular levels of free ISG15 are expected to increase due to decreased ISGylation (due to low levels of UBE1L) and increased ISG15 deconjugation (due to high levels of USP18) of cellular proteins in these cancer tissues." (PMID 35159348, 2022). "Experiments reported here uncovered an intriguing consequence of USP18 enzymatic activity affecting the biology of lung and other cancers." (PMID 35387560, 2022). "Our results provide strong evidence for USP18 in regulating antigenicity and radiosensitivity, highlighting its potential as a cancer target." (PMID 33214684, 2021). "The complex USP18-mediated regulation of cell death has diverse impacts on infectious diseases, tissue degeneration, and cancer." (PMID 33919439, 2021). "In the USP18-dependent ISGylome and proteome of cancer cells treated with type I IFN, we observed ISGylated components of the antigen presentation pathway." (PMID 33214684, 2021). "Cancer-specific survival in low USP18 expression group is longer than in high expression group, indicating that upregulated USP18 is significant risk factor for cancer-specific death." (PMID 32957626, 2020).
cancer (continued). "Along the same line, a recent report showed that IFN in combination with an G2/M inhibitor increased necroptosis in cancer cells, possibly due to delayed USP18 induction." (PMID 32945770, 2020). "Both ISG15 and USP18 are deregulated in different cancers, consistent with an important functional role for this DUB in homeostasis of growth-regulatory proteins." (PMID 27980214, 2017). "As demonstrated in the present study, both ISG15 and the deIGSlyation enzyme USP18 are upregulated by anti-cancer agents CLQ and MFQ." (PMID 27659523, 2016). "In the present study, we found that ISG15 and its deISGylase USP18 were induced by anti-cancer agents, and each alone induces cancer cell apoptosis." (PMID 27659523, 2016). "Depletion of USP18 induces immunogenic cell death by promoting cancer cell pyroptosis." (PMID 40514377, 2025). "Importantly, we screened and identified hyperoside (HYP) as a new USP18 enzyme activity inhibitor, which sensitizes cancer cells to existing targeted therapies (sorafenib and regorafenib) by inhibiting USP18 and following deISGylation of NCOA4." (PMID 40514377, 2025). "Increasing evidence has demonstrated that USP18 exerts oncogenic effects in various cancers." (PMID 40374599, 2025). "Notably, we have identified HYP as a novel USP18 inhibitor, which sensitizes cancer cells to existing targeted therapies (sorafenib and regorafenib) by directly targeting the IBB1 domain." (PMID 40514377, 2025). "We reason this approach of measuring the differential activity of USP18 combined with expression analysis can help investigate cancer types and states in which USP18 is highly activated and provide insights into the cellular context in which USP18 inhibitors can have translational potential." (PMID 39843430, 2025). "Indeed, USP18 knockdown significantly reduced SLC7A11 levels in multiple human cancer lines, but had moderate effects on SLC7A11 mRNA levels." (PMID 38959043, 2024). "Therefore, the strategy of targeting USP18 in myeloid cells holds substantial promise as a therapeutic approach in a variety of cancer types." (PMID 38455765, 2024). "Furthermore, USP18 inhibition specifically targets cancer stem cells, which are crucial for cancer recurrence." (PMID 38455765, 2024). "Consequently, the specific impact of USP18 inhibition needs to be carefully assessed for each type of cancer." (PMID 38455765, 2024). "USP18 suppression could induce cancer cell GSDME-dependent pyroptosis and suppress leukemogenesis via upregulating PLK2, an atypical ISG." (PMID 39048945, 2024). "LHX2 adjusts USP18 expression in cancers with poor prognosis." (PMID 39664521, 2024). "To investigate USP18 expression in various cancers, we used TIMER 2.0 for evaluation." (PMID 39334957, 2024). "In addition, USP8, USP15, USP9X and USP18 are also being reported by a growing number of top research institutes for their vital immunomodulatory functions in cancer progression." (PMID 37658402, 2023). "Moreover, it is important to consider that ISGylation levels are related to the deregulation of ISG15, ISGylation system enzymes, and USP18 de-ISGylase expression in cancer." (PMID 37711589, 2023). "Importantly, our scRNA-seq data revealed that LSC-like cells expressed genes related to inflammasome activation/pyroptosis, supporting the possibility that ICD induced by Usp18 depletion promotes the elimination of cancer stem cells." (PMID 36646704, 2023). "Altogether, our data supports the potential of targeting Usp18 for cancer therapy." (PMID 36646704, 2023). "Prior to investigating the potential therapeutic role of Usp18 depletion in cancer, we first determined whether this gene is a reasonable therapeutic target by testing if Usp18 depletion affects healthy cells." (PMID 36646704, 2023). "Furthermore, higher numbers of CD8+ T cells and activated CD8+ T cells in viable GFP− host splenocytes in recipients of Usp18+/Δ cancer cells were detected." (PMID 36646704, 2023).
cancer (continued). "It is possible that accumulated free ISG15 stabilizes USP18 in cancer cells expressing low levels of UBE1L and high levels USP18, which in turn removes the ISG15 degradation signal from the target proteins (e.g., Cyclin D1), consequently stabilizing these protumor proteins." (PMID 35159348, 2022). "USP18 are also related to the progression of virus-induced cancers." (PMID 36582601, 2022). "Additionally, the depletion of USP18 in IFN-treated or bortezomib-treated cancer cells increased extrinsic apoptosis through the upregulation of TRAIL transcription." (PMID 33919439, 2021). "Of note, USP18 has been demonstrated to be a positive regulator of epidermal growth factor receptor (EGFR) by inactivating microRNA-7 (miR–7) that is known to reduce the expression of EGFR mRNA in cancer cells." (PMID 32957626, 2020). "It has been reported that engineered gain of USP18 decreases cancer growth by destabilizing growth-regulatory proteins, which suggests that USP18 may alter transcribed mRNA catabolic process and translational initiation to facilitate the pathogenesis of SLE." (PMID 32984334, 2020). "In addition, USP18 functions as a deubiquitinase and stabilizes Notch1, which in turn regulates tumorigenesis and cancer progression in a Notch1-dependent manner." (PMID 33051403, 2020). "To summarize, not only the development of selective modulators of USP18 but also the supply of the rationale for combination of USP18 modulation with conventional anticancer therapy might be worthy for the treatment of cancer." (PMID 32957626, 2020). "In different cancers, consequences of USP18 repression on PTEN or other ISG15ylated proteins might differentially affect downstream signaling pathway." (PMID 27980214, 2017). "More importantly, ISG15 and USP18 induced cancer cell apoptosis." (PMID 27659523, 2016). "However, we found that ISG15 and de-ISGylase USP18 were induced by several anti-cancer agents, which was confirmed by both RT-PCR and immunoblotting assays." (PMID 27659523, 2016). "Combination with other markers, USP18 can be used to predict the cancer patients survival." (PMID 24884733, 2014). "Combined with the Ub-based DUB activity profiling data, the ISG15-based activity profiling of deISGylases and USP18 will help comprehensively investigate and define the activity-related landscape of Ubl proteases and unravel important Ub and Ubl-dependent biological processes in cancer." (PMID 39843430, 2025). "However, the role of USP18 in cancer stem cells, particularly GSCs, remains largely unexplored." (PMID 40374599, 2025). "Thus, blocking USP18 represents a possible immunotherapeutic strategy to treat cancer." (PMID 36646704, 2023). "We next assessed whether Usp18 depletion can delay cancer development." (PMID 36646704, 2023). "Notably, UBE1L is undetectable, and USP18 expression is higher in cancer vs. normal cells/tissues." (PMID 35159348, 2022). "USP18, which is also a member of the DUB family, is generally believed to promote the initiation and progression of various cancers." (PMID 40374599, 2025). "It was found that the deletion of USP18 inhibited the expression of adipose triglyceride lipase (ATGL), while increased expression of USP18 upregulated ATGL in cancer cells." (PMID 39944823, 2025). "USP18 suppression enhanced the expression of both typical and non-canonical ISGs without interacting with IFNAR2, thereby inducing pyroptosis in cancer cells." (PMID 38675828, 2024). "Our recent discovery reveals that the depletion of ubiquitin-specific protease 18 (USP18), a major negative regulator of IFN signaling, selectively induces cancer cell ICD, specifically pyroptosis." (PMID 38799433, 2024). "In malignant tumors, USP18 is elevated and activates AKT/mTOR signaling, promotes phosphorylated AKT (p-AKT) and p-mTOR protein expression, leading to cancer cell proliferation and migration." (PMID 39185411, 2024).